LINC00958 (long independently transcribed non-coding RNA 958)
Diseases named in the same sentence as LINC00958 in open-access papers (continued):
Sharing a sentence is not in itself a finding about the gene and the disease.
cancer (22 papers, 2020 to 2024). A tumor composed of atypical neoplastic, often pleomorphic cells that invade other tissues. "We selected lncRNAs that have never been associated with childhood ALL, among them LINC00958, also named bladder cancer-associated transcript 2 (BLACAT2), that was found markedly upregulated in lymph node-metastatic bladder cancer." (PMID 38884090, 2024). "We further explored the expression of LINC00958 in various cancers and the association of LINC00958 expression with prognosis utilizing an independent TCGA dataset." (PMID 36437914, 2022). "A large number of recent studies have focused on exploring the role of m6A-methylated mRNA in cancer cells, and some LncRNAs such as LINC00958, DANCR, and MALAT1 modified by m6A have also been reported." (PMID 34544449, 2021). "LINC00958 has been identified as oncogenes in some cancers, such as bladder cancer and OSCC, which were recognized to be as a sponge of miRNA to promote cell proliferation in some cancer cells." (PMID 34384029, 2021). "The high expression of LINC00958 has also been shown to promote the occurrence and development of certain cancers, including bladder cancer, oral cancer, pancreatic cancer, gastric cancer, cervical cancer and glioma." (PMID 34003875, 2021). "Among these DEirlncRNAs included in the model, some have been revealed to be related to the development of cancers, such as LINC00958, FOXF1 adjacent non-coding developmental regulatory RNA (FENDRR), LINC01116, and LINC00941." (PMID 34408216, 2021). "Although the general function of LINC00958 in cancer has become clear, the specific role of LINC00958 in EC has not yet been determined." (PMID 34003875, 2021). "LINC00958 has been found abnormally highly expressed and identified as a candidate oncogene in some cancers, such as bladder cancer and endometrial cancer." (PMID 31997940, 2020). "A study found that LINC00958 functions by interacting with miR-145-3p and modulating the miR-145-3p/CDK1 axis, thereby influencing the proliferation dynamics of the cancer cells, Another study found that the pro-proliferative function of LINC00958 is facilitated through the miR-422a/MAPK1 pathway." (PMID 39026978, 2024). "Molecular mechanisms of LINC00958 oncogenesis in various cancers." (PMID 36437914, 2022). "This suggested that LINC00958 has a potent tumorigenesis role in cancer." (PMID 35223488, 2022). "LINC00958 has been identified as an oncogene in human cancers." (PMID 33658048, 2021). "Therefore, LINC00958 might serve as a potential prognostic biomarker and therapeutic target for a variety of cancers." (PMID 36437914, 2022). "As the oncogenic function of LINC00958 has been reported in multiple cancer types, MYC/MAX, a vital oncogenic transcription factor in various cancers, may contribute to the transcriptional regulation of LINC00958 in cancer." (PMID 35223488, 2022).
LINC00958 also shares sentences with these, for which no sentence is quoted: glioma (4 papers); B-cell acute lymphoblastic leukaemia (1); colon cancer (1); gallbladder cancer (1); human papillomavirus infection (1); lung adenocarcinoma (1); non-small cell lung carcinoma (1); oral cancer (1); osteoarthritis (1); tongue cancer (1).